GPR78 (G protein-coupled receptor 78)
Description:
Orphan receptor. Displays a significant level of constitutive activity. Its effect is mediated by G(s)-alpha protein that stimulate adenylate cyclase, resulting in an elevation of intracellular cAMP.
Tractability: Small molecule: it belongs to a druggable protein family. Antibody: UniProt places it where antibodies can reach, with medium confidence; UniProt predicts a signal peptide or a membrane-spanning region; its Gene Ontology location is reachable by antibodies, with medium confidence.
Target class: Family A G protein-coupled receptor; Membrane receptor
Gene: Protein-coding gene on chromosome 4 (8,558,725 to 8,619,761, forward strand). Ensembl gene ENSG00000155269.
Subcellular location: Cell membrane
Gene Ontology:
Molecular function: G protein-coupled receptor activity; protein binding
Biological process: adenylate cyclase-activating G protein-coupled receptor signaling pathway; G protein-coupled receptor signaling pathway
Cellular component: membrane; plasma membrane
Genetic constraint (gnomAD): Loss-of-function variants: 26 observed, 13.45 expected, observed/expected ratio (o/e) 1.93, 90% interval 1.33 to 1.98. The synonymous counts are far from expectation, so gnomAD's model fits this gene poorly and the ratio says little. Missense variants: 640 observed, 468.57 expected, observed/expected ratio (o/e) 1.37, 90% interval 1.28 to 1.46. Synonymous variants: 346 observed, 230.19 expected, observed/expected ratio (o/e) 1.5, 90% interval 1.38 to 1.64.
Homologues: Orthologues: chimpanzee GPR78 (99% identical), macaque GPR78 (90% identical). Paralogues in human: GPR26 (46% identical), GPR63 (20% identical), GPR45 (19% identical).
Diseases named in the same sentence as GPR78 in open-access papers:
GPR78 is named in the same sentence as 34 diseases in open-access papers, as found by Europe PMC text mining. Sharing a sentence is not in itself a finding about the gene and the disease. The quoted sentences say what the papers report.
lung carcinoma (7 papers, 2019 to 2025). "GPR78 can promote lung cancer cell migration and metastasis by activating the Gαq-Rho GTPase pathway." (PMID 40689396, 2025). "Recently, GPR78 was testified highly expressed in lung cancer cell, and knockdown of GPR78 prominently suppressed cell migration and metastasis." (PMID 32117723, 2020). "GPR78 activates the Gαq-Rho GTPase pathway to promote lung cancer cell migration and metastasis." (PMID 35535309, 2022). "In addition, inhibition of GPR78 can enhance macrophage infiltration, suggesting a potential link between fatty acid metabolism and cancer immunity, which means GPR78 may serve as a potential drug target against metastatic human lung cancer." (PMID 37164974, 2023). "However, the specific function of GPR78 is still largely unknown, although it has been shown to play a role in lung cancer metastasis." (PMID 31413261, 2019).
breast carcinoma (3 papers, 2022 to 2025). "In summary, BiP/GPR-78 has been implicated in response to stress caused by nutrient deprivation, hypoxia, or resistance to chemotherapy in breast cancer." (PMID 36547124, 2022).
schizophrenia (3 papers, 2012 to 2024). A major psychotic disorder characterized by abnormalities in the perception or expression of reality. "Studies have shown that the GPR78 gene is linked to bipolar affective disorder (BPAD) and schizophrenia in a large Scottish family." (PMID 38882525, 2024). "GPR78, an orphan G-protein coupled receptor, is situated in an area of chromosome 4p where have been shown connection to schizophrenia and bipolar affective dysfunction." (PMID 32117723, 2020).
gastric cancer (2 papers, 2017 to 2022). A primary or metastatic malignant neoplasm involving the stomach. "GPR78 protein expression was positively correlated with depth of invasion, lymph node metastasis, TNM staging and dedifferentiation of gastric cancer, but versa for GRP78 mRNA." (PMID 29069845, 2017).
hepatocellular carcinoma (2 papers, 2018 to 2026). A malignant tumor that arises from hepatocytes. "Also, activation of GPR78/BiP, XBP1 and ATF6 were observed in hepatocellular carcinoma cell line compared to non-cancerous liver tissues." (PMID 30081573, 2018).
prostate carcinoma (2 papers, 2022 to 2023). A carcinoma that arises from epithelial cells of the prostate gland. "N-cad suppression by GPR78 has been shown to significantly reduce the adherence of prostate cancer cells to osteoblasts." (PMID 35055079, 2022). "Moreover, the results of this study also suggest that the increased expression of GPR78 is a predictive factor for prostate cancer recurrence in patients who were diagnosed with the cancer at an early age." (PMID 35055079, 2022). "The silencing of GPR78 expression via siRNA in prostate cancer cells (in bone metastatic PCa cell line, PC3) reduces the level of the adhesion protein N-cadherin (N-cad), the participation of which has already been confirmed in metastasis and castration resistance PCa cells." (PMID 35055079, 2022).
colitis (1 paper, 2021). Inflammation of the colon. "The RT-qPCR results showed that ghrelin reduced the mRNA expression of GPR78, CHOP, and BAX and increased the mRNA expression of Bcl-2 in a dose-dependent manner in mice colitis models, and such an effect of ghrelin could be reversed by [D-lys3]-GHRP-6." (PMID 33776781, 2021).
Diabetes (1 paper, 2025). "Diabetes caused an elevation in the level of expression of the GPR78 gene in line with an increase in the level of glucose, iron, and ketone bodies, leading to a higher fungal growth rate." (PMID 40488471, 2025).
diabetic neuropathy (1 paper, 2021). A chronic, pathological complication associated with diabetes mellitus, where nerve damages are incurred due to diabetic microvascular injury involving small blood vessels that supply these nerves, resulting in peripheral and/or autonomic nerve dysfunction. "This shows that EA could significantly inhibit the upregulation of GPR78 and caspase-12 in diabetic neuropathy." (PMID 34445280, 2021).
ER stress (1 paper, 2017). "Meanwhile, H2S inhibited the expressions of ER stress-related proteins, GPR78, Chop and cleaved caspase-12 level, in the hippocampus of CRS-exposed rats, which indicated H2S protects CRS-generated hippocampal ER stress." (PMID 29245987, 2017).
Genetic obesity (1 paper, 2022). "To confirm that the release of HSP70 and GPR78 was dependent on lipid consumption, we assessed their serum levels in Zucker Diabetic Fatty (ZDF) rats, which are commonly used as research model of genetic obesity and T2D." (PMID 36513656, 2022).
glioblastoma (1 paper, 2018). The most malignant astrocytic tumor (WHO grade IV). "For instance, Epigallocatechin 3-gallate, a polyphenolic green tea component, increased the apoptotic activity of temozolomide in glioblastoma cell death through inhibition of GPR78/BiP." (PMID 30081573, 2018).
Hypoglycemia (1 paper, 2008). A decreased concentration of glucose in the blood. "Interestingly, pyrvinium did not suppress the GPR78/94 induction by tunicamycin, demonstrating that the pyrvinium effect is limited to specific stress conditions of hypoglycemia and glycolysis inhibition." (PMID 19079611, 2008).
Lewy body dementia (1 paper, 2019). A progressive form of dementia characterized by the presence of protein deposits called Lewy bodies in the midbrain and cerebral cortex, and loss of cholinergic and dopaminergic neurons. "Unlike the previous Lewy body dementia study, the present investigation reports reduced cortical protein, but increased transcript levels of GPR78 in PD." (PMID 31333410, 2019).
liver cancer (1 paper, 2012). An epithelial or non-epithelial malignant neoplasm that arises from the liver. "The polyclonal anti-GPR78 antibody was used as primary antibody to detect the expression of GRP78 in liver cancer and normal hepatic tissues." (PMID 22692946, 2012).
mucormycosis (1 paper, 2025). "Furthermore, the expression of the GPR78 gene in the sinus tissue of diabetic patients infected with untreated mucormycosis was higher than that in the normal tissue of the same patients." (PMID 40488471, 2025). "The relative expression of the GPR78 gene was about 117 times higher in sinus tissue of mucormycosis-infected patients not treated with LAmB compared to control (the normal parts of the same infected tissue)." (PMID 40488471, 2025).
pressure ulcers (1 paper, 2020). "Recently, the ER stress proteins (PDI and GRP78) were found to be involved in the formation of pressure ulcers, and the levels of PDI and GPR78 were associated with the severity of pressure ulcers." (PMID 33354279, 2020).
renal carcinoma (1 paper, 2025). A carcinoma arising from the epithelium of the renal parenchyma or the renal pelvis. "Proteasome inhibitors can suppress the growth of renal cancer cells by modulating the gene expression of EDEM1, a downstream effector molecule in the unfolded protein response (UPR), through inhibition of GPR78 expression." (PMID 41040512, 2025).
Stroke (1 paper, 2017). Sudden impairment of blood flow to a part of the brain due to occlusion or rupture of an artery to the brain. "For example, increased miR-181a exacerbated injury both in vitro and in a mouse stroke model by targeting G protein-coupled receptor 78 (GPR78)." (PMID 29057271, 2017).
cancer (8 papers, 2008 to 2023). A tumor composed of atypical neoplastic, often pleomorphic cells that invade other tissues. "GPR78 is also implicated in oncogenesis, cancer progression, and drug resistance." (PMID 27016417, 2016). "A number of molecular chaperones are up-regulated in cancer in response to ER stress, including heat shock proteins (such as GPR78 and GPR94) and lectin-like chaperones (such as calnexin and calreticulin)." (PMID 30115016, 2018). "In fact, in many cancers, glucose-regulated protein 78 (GPR78, an ER protein chaperone involved in adaptive response to ER stress) is overexpressed and correlates with cancer recurrence, therapeutic resistance, and stemness phenotype." (PMID 28275367, 2017). "By activating UPR, cancer cells upregulate proteins such as GPR78 and GPR94, thus promoting ubiquitination degradation of CHOP protein, reducing the activity of CHOP, and restoring the folding environment and protein balance of ER protein, thus enabling cancer cells to survive." (PMID 36551309, 2022). "Since GPR78 induction constitutes one of the key pro-survival mechanisms of cancer cells in response to glucose deprivation, PST-A and B-induced suppression of GRP78 expression may result in cell death." (PMID 32482939, 2020). "Since GPR78/94 induction constitutes one of the key pro-survival mechanisms of cancer cells in response to glucose deprivation, pyrvinium-mediated suppression of GRP78 and GRP94 expression may counter this survival mechanism and resulted in rapid cell death." (PMID 19079611, 2008).
tumor (3 papers, 2015 to 2022). "The results showed that the expression of GPR78 in tumor tissues was strongly higher than that in normal tissues, and GPR78 expression was significantly negatively correlated with tRF-24-V29K9UV3IU (P < 0.001)." (PMID 35535309, 2022). "This indicates that the overexpression of GPR78 renders the tumor cells resistant to apoptosis and hormone therapy, thereby leading to the growth of a castration-resistant tumor." (PMID 35055079, 2022). "Since this has become the standard of care, the correlation between the novel tumor marker GPR78 and a popular gene set, the Oncotype DX, was studied." (PMID 26622810, 2015). "Therefore, it is reasonable to speculate that GPR78 is involved in the regulation of tumor progression, and this has been partially confirmed." (PMID 35535309, 2022). "To interrogate whether the expression of GPR78 and tRF-24-V29K9UV3IU is correlated in tumor tissues, we examined GPR78 expression in 19 paired tumor tissues and normal tissues, followed by Pearson's analysis." (PMID 35535309, 2022).
infection (2 papers, 2020 to 2025). The state of being infected such as from the introduction of a foreign agent such as serum, vaccine, antigenic substance or organism. "As for the GPR78 gene, results indicated an increased expression in the tested samples, and this increase is positively associated with the period of time since infection." (PMID 40488471, 2025). "Whereas one of the probable targets of hsa-miR-16–5p is the ATK gene associated with the GPR78 signaling pathway, the increased expression of GPR78 after 6 and 16 h of infection decreased the hsa-miR-16–5p expression through a suppressive effect." (PMID 40488471, 2025).
bacterial infection (1 paper, 2019). "For example, increased expression of BiP and other chaperones during acute-phase response in mice with bacterial infection was regulated by binding of Signal Transducer and Activator Of Transcription 3 (STAT3) directly to Gpr78 promoter." (PMID 30908491, 2019).
GPR78 also shares sentences with these, for which no sentence is quoted: laryngeal squamous cell carcinoma (2 papers); bipolar affective disorder (1); bladder cancer (1); colon cancer (1); fungal infection (1); glioma (1); Hepatic steatosis (1); Insulin resistance (1); lymph node metastasis (1); melanoma (1); Obesity (1).